IL5 (interleukin 5)
Diseases named in the same sentence as IL5 in open-access papers (continued):
Sharing a sentence is not in itself a finding about the gene and the disease.
asthma (continued). "Many studies have shown that type 2 cytokines, including interleukin (IL)-4, IL-5, and IL-13, were related to allergic inflammation and these cytokines elevated in the sputum and the blood of patients with asthma and AR." (PMID 35348596, 2022). "Among them, Th2 cells play a major role in asthma pathogenesis by secreting various cytokines such as IL-4, IL-5, IL-9, and IL-13, while IFN-γ secreted by Th1 inhibits Th2 function." (PMID 35815290, 2022). "Clinical studies have investigated Th2 cytokine inhibitors, including IL-5 inhibitors, in asthma therapy." (PMID 35313976, 2022). "This idea is further supported by the successful clinical application of anti-IL-5 monoclonal antibodies in the treatment of asthma patients." (PMID 36016937, 2022). "As noted, asthma is also a manifestation of excessive activation of Th2 cells, which leads to increased secretion of IL-4, IL-5, and IL-13 in asthmatic mice." (PMID 35682783, 2022). "Epithelial cytokines known as alarmins resulted in the production of IL-4, IL-5, and IL-13, which play key roles in asthma pathogenesis." (PMID 36077310, 2022). "High levels of IL-5 have been detected in serum of patients with severe asthma, in whom eosinophilopoiesis occurs not only in the bone marrow but also in the airways." (PMID 36140282, 2022). "After cortisol hormone therapy, the levels of IL-4, IL-5, and IL-8 in the sputum of asthma patients were reduced, IL-13 expression was decreased in the bronchial epithelium in asthma patients." (PMID 35578178, 2022). "Data from 17 adult patients with severe asthma and treatment with anti-IL-5 biologics were analysed on the day before the first administration, and 16 weeks after the introduction of the drug." (PMID 35055384, 2022). "Inflammatory phenotyping has become essential in the clinical assessment of asthma, identifying patients that will respond to corticosteroid and IL-5 targeting therapies." (PMID 36294774, 2022). "Patients with asthma experienced induction of type 2 (T2) inflammation, as illustrated by increased nasal IL-5 concentrations and elevated eosinophil counts in bronchoalveolar lavage fluid measured 4 days post-inoculation." (PMID 35082127, 2022). "Then, in the experiment of PEF against asthma, our findings showed that the expression of IgE, IL-4, IL-5, IL-6, IL-13, and IL-17 were significantly higher in the model group." (PMID 36172200, 2022). "While IL-1β is an inflammatory protein, IL-5 and eotaxin are both involved in allergic inflammation and asthma, but they are involved in breast cancer progression as well." (PMID 36158648, 2022). "Otherwise, asthma mice pretreated with Imuno TF presented reduced concentrations of IL-4 (5A), IL-5 (5B), and IL-13 (5C) in lung tissue compared to asthma mice." (PMID 36685604, 2022). "Mepolizumab (Nucala) is the first approved monoclonal antibody (mAb) targeting IL-5, blocking the binding of IL-5 to IL-5Rα, which reduces blood eosinophil counts and exacerbations of asthma and improves asthma control." (PMID 36403040, 2022). "Through transcriptional analysis, it was found that the asthma group had upregulated IL-4, IL-5, and IL-10 expression in lung tissue than the normal group, while MS treatment augmented IL-10 and attenuated the elevation of IL-4 and IL-5." (PMID 35812246, 2022). "Type 2 CRSwNP patients are characterized by the presence of staphylococcal enterotoxin immunoglobulin E (SE-IgE) and type 2 cytokines such as IL-4, IL-5 and IL-13, as well as high asthma comorbidity and recurrence." (PMID 36618395, 2022). "Among the various factors related to asthma progression, the Th2 cytokines including IL-13, IL-5, and IL-4 play crucial roles in the advancement of the disease." (PMID 35892624, 2022). "The asthma prevalence correlated positively with IL-5 levels and the presence of Staphylococcus aureus enterotoxin specific-IgE (SE-IgE)." (PMID 35455762, 2022).
asthma (continued). "Relevant to the present review is the consideration of potential predictors of good asthma response among anti-IgE, anti-IL-5, anti-IL-4R and anti-TSLP therapy, if locally accessible and cost-effective." (PMID 35743783, 2022). "These cytokines associated with the Th2 response induce IgE immunoglobulin production by B lymphocytes (IL-4), chemotaxis for eosinophils towards the lung microenvironment (IL-5), mucus and collagen secretion, and bronchial hyperreactivity (IL-13)." (PMID 36685604, 2022). "HES treatment in an ovalbumin (OVA)-induced asthma mouse model reduced IL-4, IL-5, IL-13, and IL-17 production, as well as OVA-specific IgE expression by inhibition of the GATA binding protein 3 (GATA3) transcription factor to the DNA." (PMID 35631330, 2022). "Th2 cells secrete IL-4, IL-5, IL-9, IL-13 and other inflammatory factors, among which IL-4 and IL-13 are the regulators of asthma." (PMID 35744915, 2022). "Recent therapeutic advances in the management of asthma have underscored the importance of eosinophilia and the role of pro-eosinophilic mediators such as IL-5 in asthma." (PMID 34739571, 2021). "We also investigated the effect of VitD supplementation on the expression of proinflammatory cytokines involved in asthma pathogenesis, including Th2 cytokines (IL-4 and IL-5) and Th17 cytokines (IL-17A and IL-17F)." (PMID 34395637, 2021). "On the contrary, neutralization of IL-5 by a monoclonal antibody blocked asthma-induced resolution of arthritis, with a reduced expansion of rEos in the joints." (PMID 34733292, 2021). "Much of the eosinophil’s involvement in airway dysfunction in asthma comes from the actions of IL-5, which has become an effective target in therapy." (PMID 34572281, 2021). "Several reports have shown that this parameter is capable of predicting severe asthma exacerbations, as well as responsiveness to inhaled corticosteroids (ICS) or novel biologic treatments for severe asthma, focused on IL-5 or eosinophils." (PMID 34209213, 2021). "We now understand that, depending on disease severity, 40%–70% of patients with asthma exhibit heightened Type-2 (T2) inflammation, which clinically improves with IL-4– and IL-5–targeted therapies." (PMID 34591794, 2021). "Mepolizumab, a fully humanized monoclonal IgG1 kappa anti-IL-5 antibody approved for severe asthma and hypereosinophilic syndrome, has been studied in both adult and pediatric EoE." (PMID 35095572, 2021). "Nowadays, available biological asthma therapy is reserved for T2-high asthma; it targets allergy molecules IgE and eosinophilic interleukins (IL-5, IL-4, IL-13, TSLP)." (PMID 34070316, 2021). "Pathophysiological and inflammatory processes in T2-high asthma are represented by a high level of type 2 cytokines: IL-5, IL-4, IL-13, IL-25, IL-33, and thymic stromal lymphopoietin (TSLP)." (PMID 34070316, 2021). "Th2-dominant responses, with increased Th2 (IL-4, IL-5, and IL-13) cytokines and IgE production, are characteristic immune responses in patients with allergic diseases such as food allergy, asthma, and AD." (PMID 34356353, 2021). "The aim of the study is to review the immunopathology and treatment efficacy for severe asthma and focused on new biological agents with benralizumab (anti-IL-5) and tezepelumab (anti-TSLP)." (PMID 34440488, 2021). "Functional analysis of these epigenetic modifications confirmed the role of IL-5 (IL5RA) and potassium voltage gated channels (KCNH2) for the predisposition to asthma." (PMID 34834581, 2021). "Recent studies and post-hoc analyses have shown that patients whose asthma did not respond to omalizumab can improve with a biologic treatment targeting the IL-5 pathway in terms of asthma control, exacerbations, and OCS reduction." (PMID 34922515, 2021). "It was already reported that this key cell of the allergic response during asthma, the eosinophil, is activated by cytokines (IL-5) and chemokines (CCL5, CCL11) via the activation of MSK1." (PMID 33450992, 2021).
asthma (continued). "Ozone has been shown to aggravate AR and asthma by inducing the release of IL-5 and IL-13 from ILC2s." (PMID 34177881, 2021). "In comparison to mild asthmatics, higher numbers of ILC2-expressing IL-5 and IL-13 have been detected in patients with severe asthma and persistent airway eosinophilia, despite high-dosage OCS therapy." (PMID 33922072, 2021). "Eosinophilic inflammatory response, which is characteristic of asthma, is known to be induced by IL-4, IL-5, and IL-13 produced by CD4+ T helper type 2 (Th2) cells." (PMID 34576095, 2021). "In particular, for quite some time the spotlight has been on IL-5, for its an important role in asthma." (PMID 35126131, 2021). "Our results indicate that HDM-induced IL-5 production can be considered as a predictor for the presence of atopy in children with asthma, as has been suggested by others." (PMID 34220812, 2021). "An increase in the levels of Th2 cytokines (IL-4, IL-5, and IL-13, among others) and Th17 cytokines (IL-17 and IL-6, among others) was observed in both patients with asthma and animal models of asthma." (PMID 34526979, 2021). "Given the association of IL-4, IL-5, IL-9, IL-13 and TSLP to asthma pathologies, all have been targeted with antibody-based therapeutics that bind either directly to the cytokines or their receptors." (PMID 34680614, 2021). "Mepolizumab and benralizumab are antibody preparations that target IL‐5 and IL‐5Rα and have been used in the treatment of asthma." (PMID 34363652, 2021). "Instead, the other biologic drugs approved by the EMA are indicated for specific Type 2 severe asthma phenotypes (e.g. “Allergic” for anti-IgE or “Eosinophilic” for anti-IL5)." (PMID 34020658, 2021). "Antibodies for neutralizing IL-4, IL-5, IL-13, and IgE were considered as personalized medicine to improve asthma patient status." (PMID 34595240, 2021). "Anti-IL-5 therapy as a method of asthma treatment has been introduced over the past decade for the treatment of severe eosinophilic asthma." (PMID 33917396, 2021). "Cytokine or cytokine receptor targeting by therapeutic antibodies, such as anti-IL-4 and anti-IL-5, is now approved for severe asthma treatment." (PMID 34084159, 2021). "For example, patients switched from anti-IL-5 to anti-IL-4/IL-13 had worsening in asthma control and showed increased use of OCS, with substantial increases in peripheral eosinophils." (PMID 35126131, 2021). "This includes more Th1 cytokines (IFN-γ and IL-2) combined with fewerTh2 cytokines (IL-4 and IL-5), correlated with significantly higher NK cell cytotoxicity as compared to the asthma group." (PMID 33919400, 2021). "Chronic airway inflammation in asthma is typically characterized by eosinophil infiltration, overproduction of IgE, and Th2 cytokines, including IL-4, IL-5, and IL-13." (PMID 35008504, 2021). "Atopic diseases such as atopic dermatitis, allergic rhinitis, and asthma involve an uncontrolled type 2 inflammatory response mediated by the Th2 cytokines IL-5, IL-13, and IL-4." (PMID 34238943, 2021). "The Th2 pathway in asthma can be recognized by increased secretion of IL-4, IL-5, and/or IL-13 resulting in eosinophilic inflammation." (PMID 35387016, 2021). "Treatments with kaempferol attenuated the Th2-driven allergic airway disease in an experimental model of asthma by decreasing production of IL-5 and IL-13 and amelioration of airway hyperresponsiveness (AHR) induced by OVA challenge." (PMID 34552650, 2021). "Novel biologics such as IL5 and IL-4/IL-13 pathway-targeting therapies have made essential the phenotyping of severe asthma, according to GINA guidelines." (PMID 33815653, 2021). "In a mouse model of asthma, IL-25-induced ILC2s and IL-33-induced ILC2s contributed 50~80% of the total IL5 and IL-13 production in the lung, although stimulation with IL-25 or IL-33 separately did not cause excessive lung reactions." (PMID 34177881, 2021). "IL-4, IL-5 and IL-13 are the central Th2 cytokines responsible for eosinophilic inflammation in asthma." (PMID 34084159, 2021).
asthma (continued). "Among those biomarkers, monoclonal antibodies against IL-4 and IL-5 have been developed for the treatment of asthma." (PMID 34516405, 2021). "Anti-IL-5 therapy was significantly more effective in reducing the annual exacerbation rate in asthma patients than in eosinophilic COPD patients." (PMID 34795588, 2021). "T2 asthma is characterized by airway inflammation driven by T2 cytokines including interleukins IL-4, IL-5, and IL-13." (PMID 33513844, 2021). "A prospective study on a small sample found interleukin (IL)-5 of EBC having a significant predictivity of asthma exacerbation." (PMID 33925009, 2021). "In contrast, asthma pro-inflammatory cytokines such as IL-4, IL-5, IL-13, and IL-33 contribute to maintain the lean state." (PMID 33418879, 2021). "Eighty percentage of children and 60% of adults with asthma have type 2/Th2 asthma, which is driven by allergen-induced production of IgE and Th2 cytokines, including IL-5, IL-13, and IL-4." (PMID 33643321, 2021). "We prospectively evaluated the efficacy and safety of a low dose (100 mg q4w), 12-month course of mepolizumab, an anti-IL-5 monoclonal antibody, in eight patients with severe asthma and active EGPA." (PMID 34162391, 2021). "p38 is able to induce the differentiation and activation of Th2 in asthma, resulting in the facilitated release of cytokines (IL-4, IL-5, and IL-13) secreted by Th2 cells." (PMID 34629023, 2021). "Increased serum levels of IL-8, as well IL-4, IL-5, and IL-9 have been reported in asthma hyperreactivity following Th2 lymphocyte release." (PMID 34884340, 2021). "Unfortunately, no studies thus far have looked at the efficacy of combining anti-IL-4/IL-13 and anti-IL-5 biologics for asthma treatment." (PMID 35126131, 2021). "This approach avoids autoimmune-mediated worsening of asthma, which has previously been reported with low dose anti-IL-5 therapy." (PMID 33917396, 2021). "In contrast to some models that measured IL-4, in our model we measured the Th2 response through IL-5 and IL-13, because they were able to envelop the parameters of asthma." (PMID 34829186, 2021). "T2-high (IL-4–, IL-5–, IL-13–driven) asthma is typified by eosinophilic inflammation, while T2-low disease has been linked to neutrophilia and molecular signals such as type 1 IFN and IFN-γ." (PMID 34591794, 2021). "A strong correlation between symptom control and salivary levels of eotaxin, IL-5 and IL-8 was reported in both children and adults with asthma." (PMID 33925009, 2021). "These are therapies derived from the development of a new target of interventions on a specific pathway of the asthma endotypes that include immunoglobulins E (IgE) and interleukin-5 (IL-5) and its receptor, as well as the IL-4 receptor." (PMID 34572281, 2021). "The approved humanized monoclonal antibodies (mAbs) for the treatment of asthma are targeted against IgE (omalizumab), IL-5 (mepolizumab and reslizumab), IL-5 receptor α (IL-5Rα; benralizumab), and IL-4/IL-13 (dupilumab)." (PMID 34572466, 2021). "BAL IL‐4 and BAL IL‐5 were both increased in the high BAL IL‐13 group compared with the low IL‐13 severe asthma group." (PMID 33411348, 2021). "Comparatively, allantoin, another purine metabolite, attenuated lung inflammation (↓eosinophils, lymphocytes and inflammatory cell influx), IgE and Th2 cytokines (IL-4, IL-5) in BALF of ovalbumin-induced lung inflammation in murine models of asthma." (PMID 33919626, 2021). "Many asthma-relevant cytokines, including IL-4, IL-5 and IL-13, depend on JAK signaling to elicit an inflammatory response." (PMID 34680614, 2021). "IL-5 produced by ILC2s and Th2 cells recruits eosinophils to colon and lungs, thereby promoting asthma development." (PMID 34938670, 2021). "Two interventional strategies are available to regulate IL-5 and the eosinophil’s participation in asthma." (PMID 34572281, 2021).
asthma (continued). "Since CP and OA inhibited IL-5 in BALF and Th2 cytokine (IL-5, IL-4, and IL-13) production in spleen cells, we assessed the mRNA expression of asthma-associated cytokines and mediators in the lung tissues of OVA-induced asthmatic mice using qRT-PCR." (PMID 33806085, 2021). "Exaggerated responses were observed in PBMC isolated from children prior to asthma development in later life, including increased IL-5, IL-13, IL-17, and IL-10 when exposed to H. influenzae and Mcat." (PMID 35386999, 2021). "Summarizing, eosinophils and several cytokines like IL-5, implied in their production, migration and infiltration of the lungs, are key features of inflammation in asthma." (PMID 33921360, 2021). "Our study provides support for this, with a specific impact on asthma relevant IL-5/eosinophil pathways." (PMID 34943027, 2021). "This study also demonstrated that HDM-stimulated IL-5 release was significantly higher in children with asthma than in healthy controls." (PMID 34220812, 2021). "Exacerbations in severe asthma patients, who have blood eosinophil counts of 150 cells/μL or more, are reduced with Mepolizumab, a monoclonal antibody to IL-5." (PMID 33568198, 2021). "Asthma has historically been regarded as entirely an atopic disease involving allergic (IgE-mediated) sensitization resulting in interleukin (IL)-5 mediated eosinophilic airways inflammation, which was thought to be a cardinal feature." (PMID 35387066, 2021). "Further anti-IL-5 therapies are currently under investigation: after the successful completion of phase 3 RCTs in asthma, reslizumab (anti-IL-5), and benralizumab (anti-IL-5 a receptor) were investigated in phase 2 trials." (PMID 34796188, 2021). "In mice that lack IL-4, IL-5, IL-13 reduction of asthma symptoms was observed in the Ova-Alum experimental model." (PMID 33649900, 2021). "Biological agents (i.e. monoclonal antibodies) targeting IgE, IL-5, 4 and 13 have had a significant impact on clinical practice in severe asthma." (PMID 34646341, 2021). "Asthma is a chronic inflammatory disease, and Th2 cells, such as IL-4, IL-5 and IL-13, play key roles in asthma pathobiology." (PMID 35011278, 2021). "This case highlights the importance of achieving optimal asthma control with the established array of asthma therapies, including biologic targeted treatments against IL-5, to prevent a severe exacerbation with this novel respiratory infection." (PMID 33785055, 2021). "The effects of nicotine-containing e-cigarettes on murine model asthma increased Th2 cytokines (IL-4, IL-5, and IL-13), responsible for allergic inflammation." (PMID 33924379, 2021). "ILC2s are essential for control of helminth infections and tissue repair and are involved in pathogenesis of asthma and allergy by secretion of type 2 cytokines IL-5, IL-9 and IL-13." (PMID 34938670, 2021). "P. cocos extract or prednisolone administration in OVA-sensitized mice significantly reduced the eotaxin concentrations and IL-5, compared to the asthma group." (PMID 33919400, 2021). "In asthma, Th2 cytokines IL-4, IL-13, and IL-5 play a major role in stimulating airway inflammation, whereas Th1 cells suppress airway hyperreactivity by producing IFN-γ." (PMID 33781317, 2021). "ILC2 is of a pivotal role in promoting type 2 responses in asthma through the production of IL-13 and IL-5, with the former involved in bronchial hyperreactivity and the latter in airway eosinophilia." (PMID 33781317, 2021). "The anti-interleukin-5 antibody, mepolizumab, was introduced, resulting in the discontinuation of systemic prednisolone and good asthma control." (PMID 34721879, 2021). "Starting in 2000, a double-blind, randomized, placebo-controlled trial was conducted to investigate the therapeutic effects of a monoclonal antibody against IL-5 in asthma patients." (PMID 34829866, 2021). "Group 2 innate lymphoid cells (ILC2s) are an important source of type 2 cytokines IL-5 and IL-13, which contribute to the progress of asthma." (PMID 34305612, 2021).